MTOR (mechanistic target of rapamycin kinase)
Diseases named in the same sentence as MTOR in open-access papers (continued):
Sharing a sentence is not in itself a finding about the gene and the disease.
cancer (continued). "Exquisite sensitivity to combination treatment targeting BRAFV600E and a downstream integrative molecule such as mTOR may be seen in a defined population of cancer cells, as in the case of BCPAP cells." (PMID 26284586, 2015). "PRL-3-driven mTOR activation, in turn, could promote the metastatic development of cancers in at least two ways: increased motility and increased invasiveness." (PMID 26597054, 2015). "Therefore, inhibition of mTOR has substantial mechanistic potential to be considered overall as an anti-cancer agent." (PMID 25699174, 2015). "The mammalian target of rapamycin (mTOR) regulates the motility and invasion of cancer cells." (PMID 25996501, 2015). "Compounds targeting the mTOR pathway have the potential of application in cancer treatment." (PMID 26176608, 2015). "Aside from reports pointing PI3K/Akt/mTOR pathway to be associated with the occurrence of multidrug resistance, it has long been known that inhibition of the mTOR pathway could trigger cancer autophagy." (PMID 26098947, 2015). "Besides emerging as a key negative regulator of autophagy, mTOR had also proved to be a potential regulator of apoptosis in various cancer cells." (PMID 26436418, 2015). "Selective regulation of PI3K/AKT/mTOR signaling represents a promising approach for cancer and might prove useful when combined with other drugs." (PMID 25933112, 2015). "The PI3K/AKT/mTOR pathway is altered in a variety of cancers including NSCLC." (PMID 25978653, 2015). "mTOR is a central node in the regulation of critical cellular processes including protein synthesis, cell growth and metabolism, which are often aberrantly stimulated in many pathologies including cancer." (PMID 25849580, 2015). "Moreover, as pathways that regulate normal tissue growth and development are often highjacked to promote cancer, understanding mTOR function in normal mammary epithelial development will likely provide insight into its role in tumor progression." (PMID 26132202, 2015). "Collectively, our findings indicated that Sesn2 may act as a tumor suppressor gene that can inhibit cancer cell proliferation viability through the regulation of Akt-mTOR-p70S6K signal pathway." (PMID 25962159, 2015). "The protective effect of fasting may in part be due to the inhibition of the nutrient-sensing mTOR pathway in normal cells and also in vitro “fasting” and rapamycin protect normal cells and increase cytotoxicity in cancer cells." (PMID 26176887, 2015). "Indeed, previous reports on cancer trials including that in HCC demonstrated that dual inhibition of the PI3K/AKT/mTOR and RAS/MEK/ERK pathways resulted in superior therapeutic responses compared with inhibition of the individual pathways." (PMID 26287667, 2015). "This baseline level of mTOR activation might result from the genetic background of this cancer cell line or have been acquired subsequent to its initial isolation." (PMID 26473364, 2015). "Both mTOR pathways are frequently deregulated in human cancers." (PMID 25906254, 2015). "These mutations may lead to an increase in mTOR activity and thus HIF-1α protein synthesis, which may render cancer cells resistant to anti-HIF-1α therapies that affect upstream regulators of HIF-1α synthesis, such as those targeting receptor tyrosine kinases." (PMID 26469226, 2015). "Moreover, polyphenols exerted their anti-cancer and chemopreventive action through the regulation of mTOR (mammalian target of rapamycin) and the sirtuins pathways by mechanisms that mimic caloric restriction." (PMID 25859884, 2015). "A negative feedback loop resulting in the activation of AKT following mTOR inhibition might also represent a potentially unfavorable event resulting from cancer treatment with mTOR inhibitors." (PMID 26369804, 2015).
cancer (continued). "It has become increasingly clear that mTORC1 and mTORC2 exert distinct cellular functions, and that combined inhibition of both complexes may fully exploit the anti-cancer potential of targeting mTOR." (PMID 25460505, 2015). "Also downstream of RTK activation is the PI3K/AKT/mTOR pathway regulating diverse cellular functions involved in EAC cancer progression including advanced tumor stage, poor prognosis and therapeutic resistance." (PMID 26378019, 2015). "Signaling through mTOR is critical for cancer cell survival and proliferation." (PMID 25988385, 2015). "Previous reports of synergistic anti-cancer effects of HDACi with PI3K/mTOR pathway inhibitors have identified distinct mechanisms of tumor cell killing among different blood cancers, further supporting the idea that the mechanisms of synergy are context-dependent." (PMID 25576920, 2015). "It remains to be determined if additional, mTOR-independent mechanisms may also contribute to the anti-cancer effects of PR and IF dietary regimens." (PMID 26378060, 2015). "The Akt/mTOR pathway plays a crucial role in stem cell aging, and this signaling could be inhibited by ROS in cancer cells." (PMID 25789082, 2015). "mTOR – a serine/threonine kinase – is frequently dysregulated in cancer cells." (PMID 25869441, 2015). "Knockdown of mTOR in HD1B cells showed a decreased stimulatory effect on cancer cells." (PMID 25807535, 2015). "The mTOR and AMPK pathways are involved in the maintenance of cancer stem cells; thus, we investigated whether the mTOR and AMPK pathways contributes to the expression of CD133 induced by ectopic expression of CD90." (PMID 26556861, 2015). "However, mTOR clearly links proliferative signaling to protein translation and plays an important role in many cancers." (PMID 26000738, 2015). "This lack of tumor control could be due to the activation of a feedback loop reactivating AKT signaling upstream of mTOR, a well-documented mechanism of resistance to rapamycin and its analogues in various human cancers." (PMID 26337467, 2015). "Our findings demonstrated that mTOR signaling is activated in cancer stem cells and may play an important role in NPC tumorigenesis and progression." (PMID 26202311, 2015). "A companion biomarker of apoptotic response would therefore be of major value in trials with mTOR inhibitors, as these drugs may only be effective in apoptosis competent cancers." (PMID 26248051, 2015). "In addition to its better-known functions in promoting protein synthesis, MTOR is now emerging as a key regulator of cellular metabolism and cancer." (PMID 25909713, 2015). "Interestingly, tumor cells with deregulated mTOR signaling are more sensitive to mTOR inhibitors, supporting that mTOR pathway is a promising target for cancer therapy." (PMID 25738366, 2015). "Indeed, aberrant mTOR regulation has been found in a considerable diversity of cancer types, including breast, lung, and pancreatic carcinomas, as well as hematological malignancies." (PMID 26490657, 2015). "On the other hand, given the mechanistic understanding of the mTOR pathway and the evidence for mTOR inhibitor efficacy in cancer treatment, it is hypothesized that sirolimus may reduce cancer incidence in kidney recipients." (PMID 26108799, 2015). "Collectively, these findings may change the view of the pathological role mTOR plays in cancer and open doors to new therapeutic strategies." (PMID 26536660, 2015). "This mTOR driven senescence can result in a selective survival advantage to cancer cells." (PMID 25895126, 2015). "Therefore, inhibition of the PI3K/Akt/mTOR signalling pathway can be looked into as a promising tool against cancer." (PMID 26436418, 2015). "Given that mTOR inhibitors are FDA-approved drugs and an mTOR inhibitor is approved for the treatment of several cancers, these findings suggest that mTOR inhibitors will likely have multiple clinical benefits, including anticancer, antinociception/anti-cancer pain, and antitolerance/hyperalgesia." (PMID 26024835, 2015).
cancer (continued). "Among these mutations, E545K (c.1633G>A) and E542K (c.1624G>A) were found in 20 (7.0%) and 11 (3.8%) cancers, respectively; H1047R (c.3140A>G) was found in 2 cancers and was associated with an increased response to PI3K/AKT/mTOR signaling pathway inhibitors in a previous clinical trial." (PMID 25669975, 2015). "In addition, other groups have shown that inhibitors of signaling pathways such as PI3K, AKT, and mTOR actually lead to activation of MEK/ERK signaling in many cancer types." (PMID 26557664, 2015). "mTOR inhibitors have been tested in clinical trials against cancer and for management of LAM, but the feedback activation of the PI3K-Akt pathway, which occurs with mTORC1 inhibition, might had lessen their clinical utility." (PMID 24571487, 2014). "mTOR plays a critical role in the regulation of tumor cell motility and cancer metastasis." (PMID 25003395, 2014). "We hypothesized that combining radiation with the mTOR inhibitor Rap would also effectively sensitize cancer cells to apoptosis." (PMID 25009644, 2014). "The deregulation of mTOR signaling through multistep oncogenic processes may contribute to the development of the Warburg effect in many cancers." (PMID 24972138, 2014). "Therefore, mTOR inhibition is a proven antitumor strategy and is being evaluated in clinical trials for other cancer indications." (PMID 24916546, 2014). "We hypothesized that nelfinavir could be repurposed as an anti-cancer agent because of its ability to inhibit the PI3K/Akt/mTOR pathway in preclinical studies." (PMID 25327558, 2014). "Twenty signaling pathways were enriched with the criteria of 2 fold changes, which include the inositol phosphate metabolism, T cell receptor signaling pathway, phosphatidylinositol signaling system, mTOR signaling pathway, primary immunodeficiency and some cancer signaling pathway." (PMID 25279261, 2014). "Finally, as the EGFR pathway is frequently activated in cancers and can activate both mTOR and Mnk1, we treated cells with the EGFR inhibitor erlotinib." (PMID 24884945, 2014). "Dysregulation of mTOR has been assigned to carcinogenesis and thus may be involved in cancer development." (PMID 24593867, 2014). "Previous studies has indicated the involvement of mTOR signaling in the maintenance of human embryonic stem cells, NPCs, hematopoietic stem cells, and cancer stem cells." (PMID 25339866, 2014). "Thus, blocking Wnt/β-catenin and Akt/mTOR pathways as well as stat and NF-κB provide potential targets for cancer therapeutic strategies." (PMID 24505326, 2014). "Clinicopathologic characteristics of cancer patients with FBXW7 mutations and their responses to mTOR inhibitors remain unknown." (PMID 24586741, 2014). "NVP-BEZ235 targets PI3K and mTOR equally in cancer, and we postulated that the combination of a PI3K/mTOR inhibitor and an HSP90 inhibitor might cooperatively inhibit tumor cell proliferation and induce apoptosis." (PMID 24796583, 2014). "A high expression of mTOR is common in human cancers and an elevated nuclear dynamics in cancer cells might be related to deregulation of mTOR." (PMID 25294810, 2014). "Therefore, it is likely that the effects of IGFR/PI3K/Akt/mTOR vertical blockade on survivin expression and anti-cancer efficacy will be affected by the interactions of the cellular signaling network." (PMID 24387108, 2014). "Under hypoxia condition, cancer cells can produce HIFα through mTOR-dependent manner." (PMID 24804240, 2014). "The mTOR pathway is considered to be a central regulator in various malignant tumors." (PMID 24944633, 2014). "mTOR signaling has been demonstrated to participate in the switch of PKM isoforms in cancer cells." (PMID 24626155, 2014). "Likewise, some anticancer agents have been reported to inhibit mTOR signaling and induce autophagy in cancer cells by degrading many major components in the mTOR axis." (PMID 25329677, 2014). "By utilizing AMPK and mTOR signaling, cancer cells can enjoy the benefits of both pathways." (PMID 24861463, 2014).
cancer (continued). "Some anti-cancer therapies, such as PI3K/mTOR inhibitors, are known to induce autophagy in cancer cells and may also induce autophagy in tumors, potentially prolonging tumor survival." (PMID 24667972, 2014). "Activated Akt/mTOR signaling is a significant contributor to pathogenesis of cancer." (PMID 25261369, 2014). "The PI3K/Akt/mTOR pathway has a central role in cancer metastasis and radiotherapy." (PMID 25275598, 2014). "Since Mirk kinase mediates survival of some cancers, its inhibition might increase the utility of mTOR inhibitors in these cancers." (PMID 25061503, 2014). "AMPK has been established as an inhibitor of the Akt-mTOR pathway in cancer and other cells." (PMID 25026276, 2014). "Therefore, quercetin induces extensive autophagy and subsequent death in cancer cells mediated by the inhibition of proteasomal activity and mTOR signaling." (PMID 25375374, 2014). "Carnosine was also shown to react with methylglyoxal, a toxic metabolic by-product of glycolysis, as well as to inhibit cancer and aging mechanisms and the cellular respiration regulatory complex mTOR, and activate the gluconeogenic enzyme, fructose-1,6-bisphosphatase." (PMID 24877122, 2014). "Large studies have been performed to test mTOR inhibitors against cancer.The combination of mTOR inhibitors with hormone- or HER2-targeted therapies appears to be a promising strategy for overcoming resistant disease and preventing the development of resistance." (PMID 24866893, 2014). "Currently early-phase and phase I clinical trials have proved higher response rate for the cancer patients with PIK3CA mutations treated with PI3K/AKT/mTOR pathway inhibitors than for those without the mutations." (PMID 25054828, 2014). "Increased mTOR activation has been implicated in a wide variety of different cancers, and AMPK-mediated attenuation of anabolic metabolism and/or mTOR signaling by metformin may contribute to the antitumor effects of metformin in some situations." (PMID 25347702, 2014). "To examine the acute requirement for mTOR signaling in adult erythropoiesis, we treated normal mice for 3 days with either rapamycin or MLN0128, a selective, ATP competitive mTOR inhibitor that is being clinically tested as a treatment for several types of human cancer." (PMID 25201874, 2014). "Aberrant expression of the mTOR signaling pathway molecules has been found in many types of cancer." (PMID 25165983, 2014). "Biologically, mTOR is a master regulator of cellular homeostasis, cell growth and proliferation as well as metabolism in a broad range of physiological and pathological settings, including diabetes and cancer." (PMID 24481632, 2014). "The PI3K/Akt/mTOR signaling pathway is important for cancer metastasis and radioresistance." (PMID 25275598, 2014). "Therefore, MTOR as a developing therapeutic target for cancer treatment with many rapamycin analogues (rapalogs) have been submitted to clinical trials in recently years." (PMID 25375091, 2014). "Overall, the responses of EBV-positive cell lines vary when treated with mTOR inhibitors, and this may be important when considering such inhibitors as anti-cancer therapeutic agents." (PMID 24917448, 2014). "mTOR activation promotes the resistance of cancer cells to apoptosis induced by both cytokines and chemotherapeutic agents, accelerates the proliferation of a wide range of cancer cells, and facilitates the metastasis." (PMID 24626155, 2014). "It turned out that the mTOR pathway was inhibited in dense cultures of cancer cells." (PMID 25585637, 2014). "mTOR inhibitors (for example rapamycin, everolimus, sirolimus, and temsirolimus) may be useful as cancer-prevention agents." (PMID 24829621, 2014). "Moreover, mTOR inhibition can overcome acquired cancer resistance to drugs targeting topoisomersase II." (PMID 24916546, 2014). "Furthermore, mTOR signaling was found to be inactivated in OA-treated cancer cells, and mTOR inhibition is required for the effect of OA on PKM2/PKM1 switch." (PMID 24626155, 2014).